LINC01270 (long independently transcribed non-coding RNA 1270)
Gene: Long non-coding RNA gene on chromosome 20 (50,292,709 to 50,315,488, forward strand). Ensembl gene ENSG00000203999.
Diseases named in the same sentence as LINC01270 in open-access papers:
LINC01270 is named in the same sentence as 4 diseases in open-access papers, as found by Europe PMC text mining. Sharing a sentence is not in itself a finding about the gene and the disease. The quoted sentences say what the papers report.
cancer (1 paper, 2026). A tumor composed of atypical neoplastic, often pleomorphic cells that invade other tissues. "LINC01270 is a long intergenic noncoding RNA implicated in the progression of various cancers." (PMID 41828328, 2026).
infection (1 paper, 2017). The state of being infected such as from the introduction of a foreign agent such as serum, vaccine, antigenic substance or organism. "As one of only a few genes, we see LINC01270 being up-regulated during infection." (PMID 28094339, 2017).
LINC01270 also shares sentences with these, for which no sentence is quoted: breast carcinoma (1 paper); triple-negative breast carcinoma (1).